TLR2 (toll like receptor 2)
Diseases named in the same sentence as TLR2 in open-access papers (continued):
Sharing a sentence is not in itself a finding about the gene and the disease.
Stroke (69 papers, 2011 to 2025). Sudden impairment of blood flow to a part of the brain due to occlusion or rupture of an artery to the brain. "Conversely, PD-1 signaling, a major pathway protecting against CNS inflammation in MCAO, likely plays a crucial role in reducing stroke-associated TLR2- and TLR4-mediated neurotoxic factor release by activated CNS microglia." (PMID 40536592, 2025). "Toll-like receptor signaling pathway is important in mediating the formation of immune system after stroke, and previous animal experiments have shown that TLR2 or TLR4 deficient mice have less brain tissue damage after stroke than wild-type mice." (PMID 35722467, 2022). "Altered inflammation in Tlr2-deficient mice was accompanied by enhanced elements of post-stroke repair, in particular during the chronic phase of recovery, but also with delayed final consolidation of the brain lesion." (PMID 30808918, 2019). "Neurons from both TLR2 knockout and TLR4-deficient mice were protected against ischemia, and the amount of brain damage and neurological deficits caused by a stroke were significantly lesser in mice deficient in TLR2 or TLR4 compared with control mice." (PMID 25886362, 2015). "Here we report that TLR2 deficiency markedly affects post-stroke immune response resulting in delayed exacerbation of the ischemic injury." (PMID 22873409, 2012). "Although previous studies have reported smaller acute ischemic lesions in TLR2-deficient mice and/or in mice treated with TLR2 blocking antibodies, the analysis has been limited to the first 24 to 72 h after stroke." (PMID 22873409, 2012). "It is noteworthy that altered microglia/macrophage activation profiles observed in TLR2−/− mice were more pronounced at day 7 post-stroke, which coincided with the initial enlargement of ischemic lesions in TLR2-deficient mice." (PMID 22873409, 2012). "TLR4 and TLR2 are pattern recognition receptors that can be sensed by immune innate cells and activate downstream signaling inflammatory cascade, which are the most investigated receptors associated with stroke-induced inflammation response." (PMID 35185744, 2021). "On the other hand, TLR2/4 expression is associated to outcome in stroke patients." (PMID 34070533, 2021). "Specific molecules blocking TLR2/4 signaling or its endogenous danger-associated molecular patterns (DAMPs) may be a novel therapeutic strategy for post-stroke neuronal inflammation and brain injury." (PMID 28424593, 2017). "To date, it is unclear whether defective microglial activation/proliferation after stroke may affect evolution of the ischemic injury in TLR2-deficient mice." (PMID 22873409, 2012). "Interestingly, animals deficient in TLR2 or TLR4 have significantly reduced infarct sizes in several models of stroke." (PMID 21999375, 2011). "Although there are multiple receptors for HMGB1, post-stroke HMGB1 receptor studies have centered around Toll-like receptors (TLR-2 and TLR-4) and the receptor for advanced glycosylation end products (RAGE)." (PMID 38740617, 2025). "Experiments in mouse models have shown that TLR2 is similarly expressed in microglia in the lesion area, and that high expression of TLR2 exacerbates ischemic stroke lesions, increasing infarct size and further amplifying stroke-induced CNS damage." (PMID 40746532, 2025). "Our studies also revealed more than 30 fold decrease in TLR2 expression between P8 and P28 under physiological conditions, making age-dependent TLR2 contribution to stroke likely." (PMID 36705821, 2024). "TLR2 and TLR4 are associated with the production of inflammatory cytokines by monocytes, TLR4 expression is associated with infarct volume, stroke severity, and functional outcome." (PMID 37452512, 2023). "While TLR4 is mostly injurious in both experimental and human stroke, owing to its versatile heterodimerization, the role of TLR2 is more complex and it can elicit both injurious and beneficial context- and tissue-dependent effects." (PMID 36759676, 2023).
Stroke (continued). "Second, TLR2 participated in the pathophysiological process of stroke and other neurodegeneration diseases." (PMID 35873459, 2022). "In the ischemic brain, DJ-1 is released into the extracellular space from necrotic neurons within 24 h after stroke onset and makes direct contact with TLR2 and TLR4 in infiltrating myeloid cells." (PMID 34014921, 2021). "The protein–protein interaction of DJ-1 with TLR2 or TLR4 in infiltrating myeloid cells was successfully detected in the ischemic brain on day 1 after stroke onset." (PMID 34014921, 2021). "Prdx-1, Prdx-2, Prdx-5, and Prdx-6 are secreted by necrotic cells in the brain early after stroke inducing the release of pro-inflammatory cytokines, which are then recognized by TLR2 and TLR4." (PMID 34208834, 2021). "One previous study with TLR2 knock out (KO) mice, subjected to focal brain ischemia, showed the lesion size reduced at day 3, however it increased at day 7 and 14 post-stroke." (PMID 32264906, 2020). "We analyzed and compared the TLR2 signals normalized to a baseline value after stroke in young and old mice." (PMID 30413172, 2018). "After a stroke, DAMPs activate TLR2 and TLR4 in microglia to increase the production of pro-inflammatory cytokines." (PMID 30809253, 2018). "EE has also been reported to enhance recovery after stroke injury by attenuating microglia-related inflammatory responses via the Toll-like receptor 2 (TLR2)." (PMID 28399892, 2017). "Specifically, the application of TLR2 blocking T2.5 antibody in vivo demonstrated the anti-inflammatory effect of TLR2-inhibition in experimental stroke." (PMID 26849209, 2016). "We also measured the expression change profile of TLR2 in response to in vitro HMGB1 stimulation to show the role of TLR2 in monocyte activation in stroke patients." (PMID 27040385, 2016). "The data showed that the anti-TLR2 antibody is able to decrease the expression of IL-17, IL-6 and IL-33, and IL-17 and IL-33 are highly increased in stroke patients." (PMID 27040385, 2016). "To test the involvement of TLR2 in ICH-type stroke, we adopted a collagenase-induced ICH model, which is a well-characterized animal model for ICH." (PMID 25879213, 2015). "Our data are in line with the previous reports showing neurotoxic effects of TLR2 in a MCAO stroke model, yet the mechanisms of the detrimental TLR2 effects in our ICH model are distinct from those in the ischemic brain injury model." (PMID 25879213, 2015). "SP-D is known to bind TLR2 and TLR4, as well as SHPS-1/SIRPα that are all expressed on and linked to induction of TNF in microglia and macrophages and involved in stroke." (PMID 25038795, 2014). "The authors thought that the therapy with VELCADE and tPA abolished the inactivation of fibrin/fibrinogen on NF-κB by directly inhibiting stroke-activated TLR2, TLR4, and IRAK1 and suppressing inflammatory respond." (PMID 23864765, 2013). "In keeping with previous work, the results of our study revealed and confirmed that, in TLR2−/− mice, the early post-stroke period (up to 3 days after transient MCAO) is characterized by smaller infarcts." (PMID 22873409, 2012). "While previous studies were primarily focused on the role of TLR2 only in the acute phase 24 to 72 h after experimental stroke, the latter phases of the tissue response to ischemia remained unexplored." (PMID 22873409, 2012). "Studies that have utilized mice which lack either TLR2 or TLR4 suggest that, following an experimental stroke, increased TLR2 signaling enhances resistance to ischemic brain damage, whereas TLR4 activation aggravates the injurious effects of cerebral ischemia." (PMID 23251498, 2012). "Using a live imaging approach we have previously shown that microglial activation after stroke is characterized by a marked long-term induction of the TLR2 signals, thus suggesting an important role of TLR2 signaling in brain ischemia." (PMID 22873409, 2012).
Stroke (continued). "Due to a post-ischemic consolidation of the ischemic brain tissue and glial scar formation in the later phase (14 days after transient MCAO), direct stroke area of WT and TLR2−/− mice were reduced compared with 3 and 7 days after MCAO." (PMID 22873409, 2012). "As expected, TLR2−/− mice showed significantly reduced direct stroke area (37.03%) compared with WT mice 3 days after MCAO (Figure 5A5B), which is in accordance with previous reports." (PMID 22873409, 2012). "In accordance with previous studies, 24 h after stroke we observed a marked increase of the TLR2 mRNA in the area of ischemic lesion and the peri-infarct zone, showing a positive S35in situ hybridization signal." (PMID 22873409, 2012). "Likewise, the inflammatory response during stroke is attenuated by blockade of the TLR2/4 complexes and cellular fibronectin." (PMID 34829993, 2021). "Among these molecules, high mobility group box 1 (HMGB1) protein appears in the early stages of stroke and is recognized by several toll-like receptors (TLRs) like TLR2 or TLR4, which trigger an inflammatory response through the release of pro-inflammatory cytokines in an NF-κB-dependent process." (PMID 34208834, 2021). "This inhibitory pathway may reduce the release of neurotoxic factors mediated by stroke-related Toll-like receptor 2 (TLR2) and TLR4 in activated microglia." (PMID 34256773, 2021). "A previous study reported that CD36 can negatively regulate TLR2 expression following adult stroke." (PMID 32903800, 2020). "TLR2 is most prominently expressed on microglia and TLR2 signaling increases the expression of pro-inflammatory and pro-apoptotic genes in the transient middle cerebral artery occlusion (tMCAO) mouse stroke model." (PMID 31379859, 2019). "Importantly, our previous studies have demonstrated that the TLR2 signal induction represents a valid readout measure of microglia activation after stroke." (PMID 30413172, 2018). "Extracellular Prxs that are released from ischemic brain cells over 12 h after stroke may act as inflammatory DAMPs, leading to the activation of TLR2/4 on immune cells and inflammatory responses in the brain." (PMID 29207618, 2017). "However, it can be deduced that the immune system in stroke patients is in part regulated by an increased frequency of Th17 cells, which leads to increases in TLR2 and inflammatory cytokines." (PMID 27040385, 2016). "Interestingly, the enhanced expression of TLR2 on monocytes was also detected in stroke patients compared with healthy volunteers." (PMID 27040385, 2016). "miRNA-19a regulates MMP-3 via TLR2 and has angiogenic roles that may contribute to blood brain barrier breakdown and vascular remodeling post stroke." (PMID 24911610, 2014). "Clinical study showed that the level of TLR2 and TLR4 in neutrophils at 72 h and 7 days following ischemia and reperfusion was an independent indicator associated with the volume of brain infarction and prognosis of stroke patients." (PMID 23864765, 2013). "To identify whether TLR2 is indeed upregulated in microglial cells (at mRNA and protein levels) after stroke we performed a series of in situ hybridization experiments followed by double immunofluorescence analysis." (PMID 22873409, 2012). "The quantitative flow cytometric analysis indicated a significant 1.38-fold reduction in numbers of the CD45low/CD11b+ cells in stroked brains of TLR2−/− mice as compared with WT 7 days after stroke, suggesting a decrease in population of the resident microglial cells." (PMID 22873409, 2012). "The co-localization was observed in activated microglial cells situated in ischemic and peri-infarct regions of the brain at 3, 7 and 14 days post-stroke, suggesting that microglia/macrophages upregulate TLR2 in early, as well as in more chronic phases, of the brain response to ischemic injury." (PMID 22873409, 2012).
Stroke (continued). "However, comparison of the levels of microglial activation after stroke revealed a marked reduction of Iba1 immunoreactivity in the brain section of TLR2−/− mice as compared with WT mice, at both 3 and 7 days after MCAO." (PMID 22873409, 2012). "In addition, 7 days after transient MCAO, indirect stroke area was significantly larger (26.41%) in the group of TLR2−/− mice compared with controls." (PMID 22873409, 2012). "In addition, a recent investigation in humans showed that the inflammatory responses to stroke in the blood were linked to increased TLR2 and TLR4 expression on hematopoetic cells and associated with worse outcome in stroke." (PMID 21999375, 2011). "However, TLR2-induced microglial activation propagated stroke-induced CNS injury, exacerbated pain hypersensitivity after spinal cord injury, contributed to kainic acid mediated innate immune responses and hippocampal excitotoxicity, and aggravated intracerebral hemorrhage-induced brain damage." (PMID 28293064, 2017). "In conclusion, the SAA and TLR2-mediated loss of accumulation of extracellular matrix may impact the vascular processes of SMC-mediated plaque remodeling and rupture, leading to myocardial infarction and stroke." (PMID 28257481, 2017). "Besides TLR2, TLR4 is also highly induced after cerebral ischemia, TLR4 deficient mice were protected against ischemic stroke, and polymorphisms of the TLR4 gene were found to be associated with stroke occurrence in a Chinese population." (PMID 26849209, 2016). "Our findings demonstrated that TLR2 and CYP1B1 overexpression induced depressive-like behaviors in post-stroke rats." (PMID 41164411, 2025). "It has been shown that TLR2 pathway signaling is diminished after cerebral ischemia, and it has also been found that TLR2 is minimally reduced in older brains, which may inhibit M2‐like responses and thus allow for less brain remodeling and recovery after stroke." (PMID 40864831, 2025). "TLR2 and TLR4 signaling appears to be important in controlling pathogenic immune responses after stroke, and estrogen, progesterone, and vitamin D3 all regulate TLR2 and TLR4 signaling, making them therapeutic options for stroke treatment." (PMID 36212660, 2022). "In animal models of stroke, extracellular HMGB1 has been found to stimulate inflammation, albeit through TLR4 signaling instead of TLR2, as we showed here." (PMID 35573828, 2022). "The impact of SNPs in CD14 (rs2569190), NF-κΒ (rs28362491), TLR2 (rs5743708), and TLR4 (rs4986790) on the incidence of combined endpoint defined as CV death, death from stroke, MI, and stroke/TIA was evaluated." (PMID 34305452, 2021). "The current study suggests that both LTA (TLR2) as well as LPS (TLR4) pathways are activated in SVO stroke and likely contribute to inflammation either before and/or after the SVO strokes." (PMID 33753837, 2021). "Among TLR families, TLR2 and TLR4 are most studied which are closely relevant to the stroke-induced inflammatory response." (PMID 35185744, 2021). "There were three- and fivefold increases in expression of TLR2 and TLR4 in the DCAL and MCAo models respectively and DCAL stroke had the highest expression of TLR4 within the models." (PMID 33097782, 2020). "In experimental animals as well as in stroke patients, it has been shown that HMGB1, a DAMP protein and also a ligand of TLR2 and TLR4, is increased in serum." (PMID 31134076, 2019). "In the context of an experimental pre-conditioning event, systemic application of LPS, Pam3CysSK4, or CpG ODN, activating TLR4, TLR2, and TLR9, respectively, prior to an experimental stroke results in protection of the mouse brain." (PMID 25239168, 2014). "It has been documented that a marked long-term induction of TLR2 expression in microglia activation after transient MCAO, suggesting an important role of TLR2 activation after stroke." (PMID 25416145, 2014).
Stroke (continued). "Preconditioning with low doses of ligands for TLR2, TLR4, and TLR9 all successfully reduce infarct size in experimental models of stroke, including a recent study showing that a TLR9 ligand is neuroprotective in a nonhuman primate model of stroke." (PMID 21999375, 2011). "They discovered that cerebral cortical neurons expressed TLR2 and TLR4 in response to ischemia‐reperfusion injury, and that mice lacking TLR2 or TLR4 had considerably less brain damage and neurological abnormalities following a stroke than did WT control mice." (PMID 40165524, 2025). "Furthermore, neutrophil extracellular traps (NETs) activated by TLR2 and TLR4 have been shown to worsen colon tissue damage and promote thrombotic events with active inflammatory bowel disease (IBD), resulting in stroke and VD." (PMID 38736878, 2024). "Future studies will need to determine if LTA/TLR2 is expressed exclusively in small vessels, and thus potentially explain its specific role in SVO but not other causes of stroke." (PMID 33753837, 2021). "Some research also found a significant rise in TLR2 and TLR4 on peripheral monocyte after stroke." (PMID 31134076, 2019). "Although stimulation of TLRs in microglia activates functions that are important for the elimination of pathogens, microglial TLRs, particularly TLR2 and TLR4, mediate stroke-induced injury to the CNS, neuroinflammation, and neuronal damage by responding to endogenous compounds." (PMID 23589665, 2013). "Studies of stroke using animal models suggest that activation of TLRs by the release of endogenous ligands contributes to tissue injury and indicates that TLR2 and TLR4, but not TLR3, contribute to this pathological process." (PMID 23589665, 2013). "However, stroke volumes were not significantly affected by histones infusion in TLR2 KO nor TLR4 KO mice." (PMID 39201339, 2024). "As a result, TLR2 and TLR4 might be regarded as potential stroke therapeutic targets." (PMID 35510663, 2022). "Here, we show that the increased expression levels of TLR2, TLR4 and TLR8, adaptor protein MyD88, signalling protein TRAF6, TLR downstream signalling proteins such as NF-κB and MAPKs were significantly prevented in IVIg-treated animals compared to control animals following stroke." (PMID 25886362, 2015). "Although these data suggest a negative effect of TLR2 in stroke, other researchers have reported that preconditioning with a TLR2 ligand protected the brain from ischemia-reperfusion injury, possibly through a TLR2/protein kinase B mechanism-dependent signalling (TLR2/PI3K)." (PMID 35269587, 2022). "Thus, we explored whether LPS (Lipopolysaccharide) or LTA (Lipoteichoic acid) levels are elevated in different causes of stroke and correlated with CRP levels since TLR4 is the receptor for Gram-negative bacterial LPS and TLR2 is the receptor for Gram-positive bacterial LTA, respectively." (PMID 33753837, 2021). "Along with TLR2 and TLR4, increased TLR7 and TLR8 also has been noticed in blood samples of deteriorating stroke patients, but no role has been reported for TLR3 or TLR9 in ischemic injury." (PMID 31134076, 2019).